INS (insulin)
Diseases named in the same sentence as INS in open-access papers (continued):
Sharing a sentence is not in itself a finding about the gene and the disease.
gestational diabetes (continued). "When these adaptive processes are unable to compensate for the increase in insulin demand, maternal blood glucose levels rise, resulting in the development of gestational diabetes mellitus (GDM)." (PMID 31817798, 2019). "Due to normal results in all 29 patients, who had either diet or insulin, the pregnancies with gestational diabetes in our cohort were comparable to normal pregnancies." (PMID 30971199, 2019). "Insulin-dependent and gestational diabetes were found to be 174 cases (5.82%) and 186 cases (6.09%), respectively." (PMID 31652912, 2019). "Whereas, HLA-DR− memory Treg cells were increased in gestational diabetes with dietary adjustment, HLA-DR+ memory Treg cells were strongly increased in gestational diabetes treated with insulin therapy compared to healthy pregnant women." (PMID 31001255, 2019). "Gestational diabetes mellitus results from both insulin resistance and failure of the pancreatic β-cells to adapt to increased metabolic demands." (PMID 30336561, 2018). "According to Rowan and colleagues who compared the use of insulin and metformin in women with gestational diabetes, metformin is a safe option for the treatment of gestational diabetes and has a higher acceptability in patients." (PMID 30820209, 2018). "Diabetes mellitus is characterized by hyperglycemia arising from dysregulation of insulin and categorized into type 1, type 2, and gestational diabetes." (PMID 30384450, 2018). "Fasting plasma total peroxide level was significantly elevated in women with previous pregnancy (B = 0.52 ± 0.13; p < 0.001), with further increase in women with insulin-treated gestational diabetes (B = 0.36 ± 0.17; p < 0.05) (R2 = 0.419)." (PMID 30210648, 2018). "In gestational diabetes, early and sufficient intervention with insulin is the key to achieve a good neonatal/obstetrical outcome when diet therapy fails to provide adequate glycemic control." (PMID 29736403, 2018). "Although the level of insulin secretion in women with gestational diabetes, like women with normal glucose tolerance, increases, but it is not enough to overcome insulin resistance and maintenance of normal blood glucose levels." (PMID 30820209, 2018). "She had a history of gestational diabetes mellitus since the 12th week of gestation which was managed by insulin administration." (PMID 29422092, 2018). "Gestational diabetes mellitus (GDM) is known to manifest in the second half of pregnancy in the setting of profound physiologic insulin resistance." (PMID 30538674, 2018). "Inadequate intake of this vitamin increases the risk of many cancers; furthermore, PLP deprivation impairs insulin secretion in rats, whereas PLP supplementation prevents diabetic complications and improves gestational diabetes." (PMID 30271425, 2018). "The Metformin in Gestational Diabetes (MiG) RCT changed practice in many countries demonstrating that metformin had similar pregnancy outcomes to insulin therapy with less maternal weight gain and a high degree of patient acceptability." (PMID 29973490, 2018). "The administration of myo-Inositol supplement for 8 weeks in pregnant women with a new diagnosis of gestational diabetes has led to a decrease in serum levels of insulin and glucose." (PMID 30820209, 2018). "Offer insulin instead of metformin to women with gestational diabetes if metformin is contraindicated or unacceptable to the woman.”." (PMID 29973490, 2018). "Baseline patient characteristics in studies comparing glyburide vs insulin in women with gestational diabetes mellitus." (PMID 28771572, 2017). "Another study also found that higher scores of social support resulted in high adherence to insulin administration in women with gestational diabetes." (PMID 29211039, 2017). "Metformin has produced better effects on feto-maternal outcomes and glycemic control in patients with gestational diabetes in comparison to insulin." (PMID 29142561, 2017).
gestational diabetes (continued). "SHBG levels were reported to be lower in women with gestational diabetes and in those who require insulin therapy." (PMID 28279160, 2017). "Both in a rat model and humans, several genes in the insulin response pathway are differentially methylated in placenta exposed to gestational diabetes." (PMID 28072825, 2017). "With all these features metformin is a better option than insulin in our population for patients having gestational diabetes mellitus." (PMID 29142561, 2017). "Regarding the effect of breastfeeding on the glucose and insulin dynamics during the postpartum OGTT in women with recent gestational diabetes during pregnancy, most previous studies examined those dynamics at 12 weeks postpartum or earlier." (PMID 28725256, 2017). "In the N group, 20% of the women (n = 41) were diagnosed with gestational diabetes, and 21.1% (n = 8) required insulin." (PMID 28750045, 2017). "A meta-analysis was conducted to compare the management of gestational diabetes with glyburide and insulin." (PMID 28771572, 2017). "In human IUGR, maternal serum concentrations of IGF-I, insulin, and leptin are decreased while obese pregnant women and pregnancies complicated with gestational diabetes have higher serum levels of leptin, insulin, IGF-I, and decreased levels of adiponectin." (PMID 26858656, 2016). "For UCB insulin values, maternal metabolic health (healthy, obese or obese with gestational diabetes mellitus) appears to be the critical parameter, followed by neonatal body length." (PMID 27440187, 2016). "The introduction of glyburide and metformin in the treatment of gestational diabetes has profoundly altered the management approach with comparable outcomes to insulin therapy." (PMID 27057336, 2015). "Of many vitamin D extraskeletal functions, its modulatory role in insulin secretion and action is especially relevant for gestational diabetes mellitus (GDM)." (PMID 26000285, 2015). "Glyburide has replaced insulin as the first line of therapy in the treatment of gestational diabetes in the United States." (PMID 27057336, 2015). "Additionally, insulin reverses the gestational diabetes mellitus (GDM) or high D-glucose-associated stimulation of the L-arginine/NO pathway in HUVECs." (PMID 25875935, 2015). "Our aim was to evaluate the difference in pregnancy outcomes and characteristics between insulin- and diet-treated women with gestational diabetes (GDM)." (PMID 26497130, 2015). "The offspring of women who had gestational diabetes and had been assigned to either open treatment with metformin (with supplemental insulin if required) or insulin in the MiG trial were followed up at 2 years of age." (PMID 25943394, 2015). "Other studies in gestational diabetes show varying figures in terms of supplemental insulin requirement." (PMID 25874236, 2015). "In another trial, women with mild gestational diabetes between 24 and 34 weeks gestation were allocated to dietary advice, blood glucose monitoring and insulin therapy if necessary, or to a control group." (PMID 24586896, 2014). "Three of the women with gestational diabetes mellitus were being managed with insulin therapy, two with metformin and one with both insulin and metformin." (PMID 25264288, 2014). "This study investigated the relation between vitamin D3 level and the glycemic control assessed by HbA1c, blood glucose levels, Quicki and insulin in serum in gestational diabetes mellitus." (PMID 25308347, 2014). "Compared with gestational diabetes mellitus as the control group, total cholesterol and insulin were all significantly lower (P < 0.001) in Zuogui Wan gestational diabetes mellitus group." (PMID 25136475, 2014). "Compared with gestational diabetes mellitus as the control group, total cholesterol and insulin were significantly lower (P < 0.001) in gestational diabetes mellitus group." (PMID 25136475, 2014).
gestational diabetes (continued). "Insulin has produced significant effects on the placental, fetal and maternal outcomes in patients having gestational diabetes mellitus in comparison to GDMs controlled on diet and exercise." (PMID 24772119, 2014). "Pakistani women had higher fasting and postload glucose (mean difference 0.20 mmol/L, 95% CI 0.17 to 0.24; 0.37, 95% CI 0.28 to 0.45), higher fasting insulin and were more likely to have gestational diabetes (GDM)." (PMID 24948746, 2014). "Of the eligible patients, 103 (1.5%) women with pre-gestational diabetes were receiving insulin prior to the pregnancy (PGDM) and 4 patients were receiving oral medications." (PMID 26237386, 2014). "Some adipokines seem to be involved in gestational pathologies like gestational diabetes mellitus and preeclampsia by their impact on insulin sensitivity and energy homeostasis." (PMID 24695544, 2014). "In pregnancy insulin sensitivity decreases, thereby pregnant females are at greater risk to have deranged blood glucose levels and subsequently some of them develop gestational diabetes mellitus (GDM)." (PMID 24772119, 2014). "This confirms that the annual insulin cost is higher in type 2 diabetic patients than type 1 or gestational diabetes, similar to Kumamoto’s study conducted in Japan in the year 2000." (PMID 24025198, 2013). "Placental expression of MMP14 is greater in pregnancies complicated by gestational diabetes mellitus and, in vitro it is induced by insulin and IGF-II in vitro and HIF-1α." (PMID 24391823, 2013). "For this reason, the use of ILPS is a viable therapeutic option when pregnant women with type 2 or gestational diabetes need a basal insulin." (PMID 23840206, 2013). "Further, we have established, that HOMA would be an accurate measure of total insulin sensitivity thoroughout pregnancy in women with gestational diabetes." (PMID 23819910, 2013). "At the end of pregnancy, eight women with gestational diabetes continued to use only basal insulin analogue." (PMID 23840206, 2013). "Pregnancy outcome in type 2 and gestational diabetes mellitus with insulin lispro protamine suspension was similar to that with NPH insulin, except for a lower insulin requirement." (PMID 23840206, 2013). "Gestational diabetes is a metabolically heterogeneous disorder; therefore, when high fasting blood glucose values are found, treatment with a basal insulin is compulsory." (PMID 23840206, 2013). "In both diabetic mothers and in those with gestational diabetes, tight control during pregnancy with the use of diet and insulin can reduce the frequency of macrosomia." (PMID 23209925, 2012). "Women with gestational diabetes generally start their treatment with diet and lifestyle modification; when these changes fail in keeping an optimal glycemic control, then insulin therapy must be considered." (PMID 22964143, 2012). "In summary, the current study delivers evidence that CTX is higher in women with gestational diabetes compared to healthy controls and related to parameters of insulin secretion and osteocalcin." (PMID 22844418, 2012). "These substances as well as other inflammatory mediators (CRP, IL-6, PAI-1, and TNF-α) seem to play an important role in glucose tolerance and insulin sensitivity dysregulation in women with previous gestational diabetes." (PMID 22956947, 2012). "The decrease in insulin sensitivity is offset by an increase of pancreatic insulin secretion, but when this mechanism is insufficient, gestational diabetes mellitus (GDM) develops." (PMID 23272038, 2012). "Women with gestational diabetes mellitus under insulin therapy had lower circulating NT-proBNP levels than those under medical nutrition therapy or healthy pregnancies." (PMID 22397400, 2012). "An additional 27 patients were excluded for a diagnosis of gestational diabetes or for using inhaled insulin or an insulin pump." (PMID 21226935, 2011). "At present, insulin is the mainstay of the management of gestational diabetes, and oral agents are discontinued." (PMID 20089006, 2010).
gestational diabetes (continued). "The need for insulin therapy is usually less for gestational diabetes than with pre-gestational diabetes." (PMID 19426468, 2009). "While most women are able to compensate with increased secretion of insulin and experience only minor changes in plasma glucose levels, those with gestational diabetes mellitus are unable to compensate for the increased resistance and become hyperglycemic." (PMID 17705823, 2007). "Adjustment of insulin therapy in gestational diabetes to normalize postprandial glucose levels leads to a decreased rate of macrosomia and lower rates of caesarean sections." (PMID 17888133, 2007). "The efficacy and safety of insulin aspart (IAsp), a rapid-acting human insulin analogue, were compared with regular human insulin (HI) as the bolus component of basal-bolus therapy for subjects with gestational diabetes mellitus (GDM)." (PMID 17888133, 2007). "Women who have had gestational diabetes mellitus are often more insulin resistant than their normal counterparts after pregnancy and have also been found to have a defect in β-cell function (reviewed in Buchanan)." (PMID 17705823, 2007). "Our data indicate that probiotics may represent a non-invasive and safe treatment for gestational diabetes through enhancing insulin sensitivity, anti-inflammatory environment, and gut health status." (PMID 41918874, 2026). "Additionally, 201 (11.8%) women had gestational diabetes, with 43 (2.5%) receiving insulin treatment and 151 (9.3%) managing it through diet." (PMID 40771999, 2025). "Additionally, 121 (13%) women had gestational diabetes, with 19 (2.0%) receiving insulin treatment and 101 (10.9%) managing it through diet." (PMID 40771999, 2025). "In conclusion, we provide evidence that different pathophysiological mechanisms might be responsible for the development of insulin-treated versus diet-controlled gestational diabetes." (PMID 39384641, 2025). "Accordingly, in young women diagnosed with gestational diabetes, particularly those requiring insulin therapy during pregnancy or with coexisting autoimmune conditions such as autoimmune thyroid disease, routine testing for anti-islet autoantibodies, particularly GADA, should be considered." (PMID 40650275, 2025). "Taking this into account, the authors conclude that the observed improvement in insulin sensitivity is owed to the high levels of adiponectin and propose daily administration of A. scoparia extract in gestational diabetes mellitus patients in order to improve insulin and glucose metabolism." (PMID 39941696, 2025). "Finally, we found a significantly decreased substance P receptor (TACR1) mRNA expression in fetal vessel segments from patients with insulin-treated gestational diabetes." (PMID 39384641, 2025). "Moreover, women with lived experience of gestational diabetes found insulin treatment to be physically and emotionally difficult, inconvenient and cumbersome." (PMID 39473074, 2025). "Canine gestational diabetes mellitus is a rare clinical condition with few reports in the literature, characterized by elevated blood glucose levels and glucose in the urine because of low insulin secretion and increased peripheral insulin resistance." (PMID 40005887, 2025). "The mechanisms through which those EV-related miRNAs would induce gestational diabetes were hypothesized to be related to the modulation of genes involved in the regulation of the insulin resistance pathway." (PMID 40136497, 2025). "Blood samples were collected from all participants for biochemical analysis, including fasting blood glucose, postprandial blood glucose, and HbA1c levels, which can be clinical indicators for the presence of gestational diabetes mellitus, and the need for insulin treatment was recorded." (PMID 40870492, 2025). "Interestingly, the overexpression of miRNA-92a-3p in skeletal muscle cells has been suggested as a protecting mechanism in gestational diabetes, as it increases insulin-stimulated glucose uptake." (PMID 40232032, 2025).
gestational diabetes (continued). "A recent multi-centre trial found that individuals diagnosed with “early gestational diabetes” (diagnosed before 20-week gestation) experienced higher rates of insulin use and adverse outcomes compared with those with “late gestational diabetes” (diagnosed at 24–28-week gestation)." (PMID 39861424, 2025). "However, the patient’s mother had a history of polyhydramnios and gestational diabetes starting at 24 weeks of gestation, which required insulin treatment, and the infant’s birth weight was 3900 g." (PMID 40004108, 2025). "Similarly, a systematic review of intervention studies established that antioxidant supplementation has a possible effect for fasting insulin for women with gestational diabetes." (PMID 41296420, 2025). "The woman developed gestational diabetes at 20 weeks and was treated with insulin." (PMID 40406819, 2025). "Inadequate nutrient intake, maternal age, and gestational diabetes mellitus (GDM) increase the risk of PE due to changes in insulin sensitivity and blood glucose levels, which may affect blood coagulation factors and increase the likelihood of thrombotembolic events." (PMID 38792409, 2024). "Accordingly, the present study sought to elucidate the impact of maternal factors on insulin resistance markers in the first week after childbirth in women who developed gestational diabetes mellitus in comparison to those with normal glucose tolerance during pregnancy." (PMID 39599657, 2024). "Ischikawa cells were subjected to progesterone treatment (P4) and hyperglycaemic/hyperinsulinaemic treatment (GDB) modeling insulin resistance in the presence of progesterone mimicking disorders such as gestational diabetes based on the protocols of previous publications." (PMID 38883605, 2024). "However, there is a need to enhance knowledge about optimum screening time and insulin use for gestational diabetes treatment." (PMID 38420077, 2024). "Another 44.6% (n = 275) knew that insulin is one of the treatments for gestational diabetes." (PMID 38420077, 2024). "The study concluded that metformin, alone or in combination with insulin, is an effective and safe option for women with gestational diabetes who require something else, to meet their treatment goals, whether with metformin alone or with supplementary insulin." (PMID 39336874, 2024). "Since then, numerous studies have confirmed metformin’s effectiveness and safety for the treatment of gestational diabetes mellitus (GDM), particularly for high-risk patients such as overweight or obese women, highlighting its better compliance compared to insulin." (PMID 39336874, 2024). "However, for the obese women with gestational diabetes mellitus, insulin responses increase, but insulin sensitivity decreases with advancing gestation, which leads to an increase in basal glucose production." (PMID 38572473, 2024). "SMTNL1 may have therapeutic relevance to the progesterone-dependent inhibition of endometrial epithelial cell migration under hyperglycemic conditions and insulin sensitivity in the endometrium in gestational diabetes or other metabolic disorders." (PMID 38883605, 2024). "However, specific knowledge about optimum screening time and insulin use for gestational diabetes was low." (PMID 38420077, 2024). "Furthermore, these mothers were diagnosed with gestational diabetes mellitus, which required insulin therapy." (PMID 39683486, 2024). "The physiologic changes of pregnancy cause an exaggerated response, leading to more severe acidosis in starvation in pregnancy, which may also have been exacerbated by relative insulin resistance from her gestational diabetes." (PMID 39156003, 2024). "Moreover, past studies investigated a lower frequency of gestational diabetes and better insulin sensitivity in pregnant females after RYGB compared to control subjects due to weight loss and hormonal changes including GLP-1 levels." (PMID 39203840, 2024).